APOE (apolipoprotein E)
Diseases named in the same sentence as APOE in open-access papers (continued):
Sharing a sentence is not in itself a finding about the gene and the disease.
brain injury (continued). "Further, apoE peptides are small enough to cross the BBB, are well tolerated, and improve outcomes in a variety of preclinical models of acute brain injury." (PMID 27713572, 2016). "This peptide is originally modified based on COG133 (133–149 of ApoE) to extend the therapeutic window of post-TBI, which has demonstrated neuroprotective activity in several models of brain injuries, including intracerebral hemorrhage and focal brain ischemia." (PMID 36081797, 2022). "After traumatic brain injury (TBI), rodents expressing the human ApoE4 protein die more often, and those who survive do worse in cognitive tests and measurements of neurite growth compared to mice expressing the human ApoE3 protein or no human ApoE." (PMID 28321820, 2017).
ovarian carcinoma (33 papers, 2009 to 2026). A malignant neoplasm originating from the surface ovarian epithelium. "While in ovarian cancer, the expression of APOE in nuclei has been found to be significantly linked to a superior prognosis in patients presenting peritoneal effusion at the time of diagnosis." (PMID 38054821, 2023). "In our study, both of exosomal ApoE, EpCAM and Plg were detected and verified, and this proved that ovarian cancer tissue associated proteins are expressed on serum EVs and this is the foundation for further investigation of their biomarker potential." (PMID 31718609, 2019). "APOE plays role in proliferation and survival of apoE-expressing ovarian cancer cells, and APOE is also associated with AD; a neurodegenerative disease." (PMID 27875990, 2016). "ZIC encoding genes have been previously implicated in cancer development and ZIC1 is known to transcriptionally trans-activate apolipoprotein E (APOE) - a gene previously implicated in the proliferation and survival of ovarian cancer cells." (PMID 20040092, 2009). "ApoE expression is increased in the more aggressive tumor types, while knockdown of APOE in ovarian cancer cell lines resulted in cell cycle arrest and apoptosis." (PMID 40149482, 2025). "Perhaps, unsurprisingly, APOE expression has also been shown to be increased in malignant ovarian tumors compared controls." (PMID 40149482, 2025). "Contrary to the role of APOD in ovarian cancer, the overexpression of APOE was found in the sera of ovarian cancer patients in comparison to healthy individuals; this overexpression was vital for the growth and survival of ovarian cancer." (PMID 38067270, 2023). "This highlights a potential prognostic significance of nuclear APOE expression in ovarian cancer patients." (PMID 38054821, 2023). "Chen and colleagues inhibited APOE expression in vitro and reported cell cycle arrest in the G2 phase as well as the induction of apoptosis, further supporting the role of APOE in ovarian cancer cell proliferation and survival." (PMID 38067270, 2023). "ApoE was overexpressed in various ovarian cell lines and tissues, and it was essential for the growth and survival of ovarian cancer cells." (PMID 35892323, 2022). "ApoE nuclear localization has been reported in ovarian cancer cells, where it leads to better survival possibly through gene regulation." (PMID 33933071, 2021). "Knockdown of APOE in APOE‐expressing ovarian cancer cells led to G2 cell cycle arrest and apoptosis, suggesting its context‐dependent role in cell cycle progression." (PMID 31981470, 2020). "It has been demonstrated that ApoE expression is elevated both in ovarian cancer cells and in ovarian cancer tumor fluids." (PMID 31718609, 2019). "ApoE is an ovarian cancer tissue specific protein which has been recently identified as a potential biomarker in ovarian cancer." (PMID 31718609, 2019). "In ovarian cancer, suppression of ApoE decreased ApoE-induced cancer cell proliferation and survival." (PMID 31275318, 2019). "To assess the mechanism by which ECM alterations promote ovarian cancer progression, we further evaluated the tumor specimens from ApoE−/− and WT mice." (PMID 29458390, 2018). "According to previous reports, the mRNA expression of ApoE showed a moderate increase during ovarian cancer tumorigenesis." (PMID 29458390, 2018). "The goal of this study was to assess ApoE loss-mediated intraperitoneal ECM reprogramming and the function of the remodeled ECM in ovarian cancer progression." (PMID 29458390, 2018). "In ovarian cancer, overexpression of ApoE has been observed in clinical specimens, including serum, primary tumors and metastases, and ApoE is required for cell proliferation and survival." (PMID 29458390, 2018). "Responsible for cholesterol metabolism and transport, it plays a critical role in proliferation and survival of ApoE-expressing ovarian cancer cells." (PMID 30619738, 2018).
ovarian carcinoma (continued). "To explore the FAK-ERK activation in ovarian cancer progression, we treated ApoE−/− mice after ID8 engraftment with the MEK inhibitor (MEKi) PD-325901 to selectively inhibit ERK phosphorylation." (PMID 29458390, 2018). "Our results indicated that the ECM in the abdominal cavity of ApoE−/− mice displayed a remodeled phenotype, and this altered microenvironment promoted the malignant progression of ovarian cancer." (PMID 29458390, 2018). "ApoE-specific siRNA when used to halt ApoE expression, it arrested the cell cycle and led to apoptosis in an ovarian cancer cell line." (PMID 27875990, 2016). "For example, apolipoprotein-E (ApoE) was identified by multiple peptides in all five iTRAQ® experiments, and was ~1.6-fold elevated in the ovarian cancer serum pools." (PMID 20546617, 2010). "Although commonly known for its role in lipid transport, ApoE has previously been shown to be overexpressed in ovarian cancer cells where it is required for proliferation and survival." (PMID 20546617, 2010). "In ovarian cancer, APOE was shown to be essential for cell survival and proliferation." (PMID 40745073, 2026). "These could relate to cholesterol synthesis and transport mechanisms due to interactions between ApoE and its receptors or to immunoregulation as have been suggested in PCa, breast, and ovarian cancers." (PMID 40149482, 2025). "The overproduction of ApoE in ovarian cancer cells may be essential for cell proliferation and the survival of the tumors." (PMID 40149482, 2025). "In ovarian cancer, overproduction and higher levels of ApoE are thought to be important in more aggressive and metastatic forms of ovarian cancer, including serous carcinomas, considered the most diagnosed and aggressive form of ovarian cancer." (PMID 40149482, 2025). "There is increasing evidence that APOE is abnormally expressed in a variety of solid cancers and may be a biomarker for bladder cancer and ovarian cancer." (PMID 35371313, 2022). "The level of ApoE in the serum of patients with ovarian cancer was dramatically increased over healthy individuals, and as a marker, it could enhance the specificity and sensitivity of ovarian cancer diagnosis." (PMID 35892323, 2022). "Beside, ApoE is required for cell proliferation and survival in ovarian cancer." (PMID 31718609, 2019). "Knockdown of ApoE in ovarian cancer cells induced cell cycle arrest and apoptosis." (PMID 31275318, 2019). "Taken together, these studies indicate that ApoE can alter the tumorigenesis and tumor progression of various cancers and might have a role in ovarian cancer progression." (PMID 29458390, 2018). "ApoE, an essential constituent of plasma lipoproteins, is overexpressed in ovarian cancer." (PMID 30619738, 2018). "To explore whether the altered ECM in the peritoneal microenvironment of ApoE−/− mice could modulate the progression of ovarian cancer, we used an ID8 intraperitoneal allograft model." (PMID 29458390, 2018). "ApoE loss induced increased ECM deposition, which stimulated the adhesions of ovarian cancer cells." (PMID 29458390, 2018). "To investigate whether ApoE loss mediates intraperitoneal ECM alterations, we measured the ECM components of the diaphragm and omentum, which are where ovarian cancer likely spreads." (PMID 29458390, 2018). "There might be, as with PCa, evidence of a role for ApoE and the immune response in ovarian cancer." (PMID 40149482, 2025). "Furthermore, APOE could also lead to the abnormal cell proliferation of ovarian cancer by inhibiting cell cycle arrest and apoptosis." (PMID 39990672, 2025). "Besides, ovarian cancer tissue specific protein EpCAM and ApoE were also verified." (PMID 31718609, 2019).
ovarian carcinoma (continued). "Therefore, we used ApoE−/− mice to explore whether ApoE loss was involved in ECM alterations and if these alterations drive ovarian cancer progression." (PMID 29458390, 2018). "The expression level of APOE is related to the histological grade, lymph node metastasis, and FIGO stage in endometrial cancer and stimulates the malignant progression of ovarian cancer by inducing FAK - ERK activation in cell/matrix adhesion." (PMID 39650066, 2024). "In addition, five new proteins with increased expression in ovarian cancer sera were identified: alpha-1-antitrypsin (AAT), apolipoprotein E (APOE), extracellular matrix protein-1 (ECM1), inter-alpha globulin inhibitor-H3, orosomucoid-2 (ORM2)." (PMID 20546617, 2010).
neuroblastoma (32 papers, 2006 to 2025). Neuroblastoma (NB) is the most common solid, extracranial childhood tumor. "In a study with implications for sporadic AD, N2a neuroblastoma cells expressing the ApoE4 allele of the ApoE gene, the major genetic risk factor for sporadic AD, showed a reduction in the levels of all ATP synthase subunits they detected in comparison to ApoE3 controls." (PMID 32853175, 2020). "In order to better define the subcellular localization of ApoE, N2a neuroblastoma cells were initially treated with physiological levels (2.5 μg/ml) of recombinant human ApoE3 or ApoE4 for 15 min and 4 h." (PMID 37290814, 2023). "We show that internalized astrocytic ApoE localizes mostly to lysosomes in neuroblastoma cells and astrocytes, whereas in neurons, it preferentially localizes to endosomes–autophagosomes of neurites." (PMID 37290814, 2023). "ApoE opsonises neuroblastoma cells for phagocytosis by macrophages via the phagocytic receptor TREM2, to which ApoE directly binds." (PMID 34177884, 2021). "The SK-N-SH neuroblastoma cell line (APOE ɛ3/3) has been published as a cell line to study the fragmentation of apoE, and the knock-down of APOE in this cell line thus provides a cell model to understand the role of apoE." (PMID 33600562, 2021). "The SK-N-SH neuroblastoma cell line has been used as a model to study apoE fragmentation, including the apoE 25-kDa fragment that is generated by HtrA1." (PMID 33600562, 2021). "Apolipoprotein E (whose E4 allele is a major risk factor in sporadic AD) promotes GAG sulfation in cultured neuroblastoma cells, and this effect is greater for ApoE4 than ApoE3." (PMID 30619849, 2018). "In this frame, we demonstrated that Haptoglobin (Hpt), an acute-phase protein of inflammation, binds Apolipoprotein E (ApoE), influencing ApoE-mediated cholesterol trafficking in blood and in neuroblastoma cell lines." (PMID 26696835, 2015). "To investigate whether ApoE isoforms can mitigate the cytotoxic effect of S100A9 aggregates on SH-SY5Y neuroblastoma cells, we used the MTT assay to measure cell viability." (PMID 38396791, 2024). "We now show that ApoE is present in the endosome–autophagy–lysosome system of N2a neuroblastoma cells and in primary neurons and astrocytes, albeit in somewhat different subcellular patterns, with neurons showing endosome–autophagosome labeling particularly of neurites and less in lysosomes." (PMID 37290814, 2023). "In addition, a recent study suggested that reconstituted ApoE isoforms increase BACE1 levels and promote Aβ production and oligomerization in human neuroblastoma SK-NSH cells with distinct efficiency (ApoE4 ≥ ApoE3 > ApoE2)." (PMID 36817952, 2023). "Similarly, increased neuronal degradation of ApoE4 compared to ApoE3 was demonstrated in mouse neuroblastoma cells, human brain lysates, and in mice expressing ApoE under the control of the neuron-specific enolase promoter." (PMID 30700058, 2019). "Moreover CPO_ Aβ17-21 P is a more potent inhibitor of apoE-enhanced Aβ 42 cytotoxicity than Aβ12-28 P in human SK-N-SH neuroblastoma cells." (PMID 28808293, 2017). "Also, Hpt prevents ApoE and ApoA-I oxidation, and modulates ApoE-mediated cholesterol trafficking in neuroblastoma cell lines." (PMID 26696835, 2015). "Our study demonstrates that astrocyte-derived human ApoE is present at APP-processing sites, with co-localization of ApoE and human Aβ/APP-βCTF in neurons and neuroblastoma cells." (PMID 37290814, 2023). "To exclude that an APOE expression increase was a haploid HAP1 cell peculiarity, we confirmed the increased levels of APOE in the diploid human neuroblastoma cell line SH-SY5Y where we CRISPRed out the SLC25A1 gene (Figure 2CSLC25A1Δ/Δ)." (PMID 37171075, 2023). "We compared the effects of ApoE isoforms in vitro on human astrocytes, a human immortalized microglia cell line (HMC3), and the human neuroblastoma cell line SH-SY5Y." (PMID 34071762, 2021).
neuroblastoma (continued). "Results from Calcein-AM staining support our findings from the MTT assay, specifically that the presence of lipidated ApoE isoforms did not change the toxic effect of S100A9 amyloids on neuroblastoma cells." (PMID 38396791, 2024). "We found that amyloids of S100A9 are cytotoxic to neuroblastoma cells, and the presence of either ApoE isoforms does not change the level of their cytotoxicity." (PMID 38396791, 2024). "We demonstrate that internalized ApoE predominantly traffics to lysosomes in primary astrocytes and N2a neuroblastoma cells, but not in primary neurons where it localizes more to endosomes and autophagosomes of neurites." (PMID 37290814, 2023). "This drug-induced effect on cholesterol transport/export was also observed in cultured human neuroblastoma cells (SH-SY5Y), with clozapine (25 μM) and haloperidol (25 μM) enhancing the expression of ApoE about 1.9-fold (p = 0.007) and 2.5-fold (p = 0.001) at 24 hours, respectively." (PMID 19715613, 2009). "Furthermore, in neuroblastoma, APOE ε4 negatively regulates the Brain-Derived Neurotropic Factor (BDNF) through a mechanism involving the enhancement of the nuclear translocation of histone deacetylases, suggesting that APOE ε4 controls the expression of key genes involved in brain functioning." (PMID 34572474, 2021). "However, these phenotypes were not shared by SLC25A1-null neuroblastoma cells or SLC25A4-null cells, even though these cells also displayed increased APOE expression and secretion." (PMID 37171075, 2023).
synucleinopathies (32 papers, 2019 to 2026). "Even though APOE has been established as a risk factor for synucleinopathies, there are still inconclusive studies suggesting that the different alleles are more related to the decrease of cognitive function rather than motor symptoms." (PMID 39996490, 2025). "Synucleinopathies and amyloidopathies are commonly found simultaneously in the brain of PD and AD patients, hindering the effect of APOE mutations in synucleinopathies' progression." (PMID 36153580, 2022). "APOE ε4 genotype is also associated with increased risk of synucleinopathies and with tau related neurodegeneration in animal models." (PMID 33485373, 2021). "Together, these studies will address the underlying pathogenic mechanisms of synucleinopathies in human relevant models, providing guidance on apoE-targeted, mechanism-based therapy." (PMID 34453582, 2021). "Furthermore, while the SNCA locus is associated with all synucleinopathies, APOE is a genetic risk factor for DLB only." (PMID 41341545, 2025). "Given this and how sometimes synucleinopathies and amyloidopathies can coexist in the brain during neurodegeneration, it might be plausible to think that APOE variants are related to a more general neurodegenerative context." (PMID 39996490, 2025). "Summary of clinical associations between APOE alleles and α-Synucleinopathies." (PMID 38339074, 2024). "Thus, greater understanding of the physiological role of apoE in the central nervous system is critical for uncovering the underlying pathogenic mechanisms in which APOE4 aggravates synucleinopathies." (PMID 34453582, 2021). "Together with validation using human postmortem brains, our work demonstrates critical roles of apoE in brain homeostasis and offers critical insights into why APOE is a strong genetic risk factor for multiple neurodegenerative diseases including synucleinopathies." (PMID 34453582, 2021). "Crossing of A53T α-synucleinopathy model mice onto the APOE-TR lines, exacerbated behavioral and pathological metrics in animals expressing the ε4 allele, while the ε2 allele attenuated α-synuclein pathology." (PMID 41282061, 2025). "It is noted that APOE genotype regulates pathology and disease progression in synucleinopathy, with APOE ε4 exacerbating pathology and APOE ε2 protecting against α-synuclein aggregation and neurodegeneration." (PMID 37578928, 2023). "Our findings reveal the predominant role of apoE in lipid metabolism and αSyn pathology in iPSC-derived cerebral organoids, providing mechanistic insights into how APOE4 drives the risk for synucleinopathies." (PMID 34453582, 2021). "Given that synucleinopathies are a predominant pathological feature of DLB, this finding may partly explain the association between APOE-ε4 and DLB." (PMID 38334615, 2024). "The implications of APOE4 in synucleinopathies are still poorly understood, but recent studies suggest that the APOE gene regulates α-syn brain pathology independently of its effects on AD-related Aβ and tau pathology and that specifically APOE4 exacerbates α-syn pathology." (PMID 36153580, 2022). "In addition to the APOE-ε4's influence on amyloidopathy, these results are consistent with the emerging evidence indicating an independent role of APOE-ε4 in modulating α-synucleinopathy in the brain." (PMID 33178113, 2020). "Notably, the presence of LBD pathology was significantly associated with increasing age only in APOE ε4 carriers, reinforcing prior findings that APOE ε4 may modulate synucleinopathy-related processes in a manner distinct from its role in AD pathology." (PMID 40382659, 2025). "Studies on the role of APOE genotype and cognition in PD provide evidence that APOE may directly impact the pathological progression of αSyn in PD; subsequently, in vivo investigations have demonstrated an APOE ε4 mediated exacerbation of αSyn pathology in murine models of synucleinopathy." (PMID 37482615, 2023). "However, the role of APOE in human synucleinopathies is probably more complex." (PMID 33213513, 2020).
synucleinopathies (continued). "We discovered that APOE4 increases α-Syn pathology via cholesterol dysregulation, suggesting that the APOE genotype may impact whether cholesterol-lowering medications can benefit classic synucleinopathies and co-pathological presentations of pathogenic α-Syn such as AD with Lewy Bodies." (PMID 39975381, 2025). "Research has also identified that APOE-ε4 promotes synucleinopathies independent of Aβ, possibly through alterations in lipid metabolism and synaptic function." (PMID 38334615, 2024). "Supporting this observation, we have generated AAV-mediated synucleinopathy animal models expressing APOE isoforms and found increased α-SYN pathology and neurodegeneration in human APOE4 knock-in mice overexpressing α-SYN, but minimal changes in APOE2 or APOE3 mice." (PMID 35471463, 2022). "This suggests that the pathological interactions between APOE and SNCA observed in model organisms or human synucleinopathies may not be driven by genetic epistasis influencing disease susceptibility." (PMID 41341545, 2025).